XPC (XPC complex subunit, DNA damage recognition and repair factor)
Diseases named in the same sentence as XPC in open-access papers (continued):
Sharing a sentence is not in itself a finding about the gene and the disease.
melanoma (continued). "In summary, XPC expression most accurately reflected the delay in CPD repair in melanoma." (PMID 26913219, 2015). "NER function is correlated with XPC expression, suggesting altered protein expression of XPC in melanoma may contribute to the observed reduced level of NER activity in melanoma." (PMID 26913219, 2015). "As there is evidence of silencing of XPC by methylation in melanoma the aim of this study was to investigate the methylation pattern of the XPC promoter region, including the CpG island and flanking shores, and its effect on gene expression in our melanoma cell lines that display reduced GGR." (PMID 29373959, 2018). "Here we have shown that, while methylation may not be the cause of reduced XPC expression, treatment of melanoma cell lines with decitabine can restore expression, and allow for strong induction in response to carboplatin." (PMID 29373959, 2018). "Interestingly, analysis of XPC−/− SCCs did not reveal a high UVR mutation load in the promoter regions of the genome which was in contrast to that seen in UV-induced melanoma genomes." (PMID 27487145, 2016). "Interestingly, subtraction of TTCCG-related mutations revealed that these constitute a large proportion of promoter mutations in melanomas, but not in XPC -/- cSCCs, supporting a notable contribution from inhibited NER in ETS sites to the overall burden increase in promoters." (PMID 30586386, 2018). "Expression of the DNA damage recognition GGR components XPC, DDB1 and DDB2 was significantly higher in melanocytes than melanoma from 4 or 8 to 48 hours after UVB irradiation." (PMID 27487145, 2016). "The transcript levels of XPC, DDB1 and DDB2 were also quantified in melanoma tumours and compared to clinical information." (PMID 27487145, 2016). "Only one melanoma cell line showed no increase in XPC or apoptosis after the sequential combination treatment, but did express markers of senescence." (PMID 32569203, 2020). "As high methylation of the CpG island is associated with gene silencing, these very low levels of methylation in melanoma here implies that methylation of the CpG island in the XPC promoter is not responsible for reduced XPC expression." (PMID 29373959, 2018). "Regardless of the role of the XPC response and its importance, here we have identified a potential combination treatment in melanoma." (PMID 29373959, 2018). "Standard chemotherapeutics, such as cisplatin, are ineffective on metastatic melanoma and we, and others, have shown that levels of a number of NER proteins in melanoma cells are elevated in response to cisplatin: ERCC1 and XPF, XPC and DDB2, XPA (this publication)." (PMID 29254481, 2017). "Interestingly, at baseline XPC and DDB2 were expressed at similar levels in melanocyte and melanoma cell lines." (PMID 27487145, 2016). "Therefore, attenuation of GGR components XPC and DDB2 would also confer an anti-apoptotic phenotype in addition to the accumulation of DNA damage, both of which are key features of melanoma." (PMID 27487145, 2016). "Despite showing the lack of XPC protein induction across the 48hours post-UVB rendering HEMn-DP an outlier compared to the other melanocyte cell lines, the baseline expression of XPC protein was high enough in HEMn-DP to induce higher CPD and 6-4PP repair than in the melanoma cell lines." (PMID 27487145, 2016). "Expression of GGR components XPC, DDB1 and DDB2 was significantly lower in melanoma after UVB." (PMID 27487145, 2016). "In contrast all three transcripts were not significantly induced in melanoma cell lines, except XPC in Mel-RM at 48 hours, after UVB treatment." (PMID 27487145, 2016).
melanoma (continued). "The possibility that ATR-dependent phosphorylation of various substrates, including XPA and/or XPC, might regulate NER exclusively during S phase specifically in melanoma cells is currently under investigation." (PMID 24416382, 2014). "We have previously reported that XPC does not respond to DNA damage in melanoma, which may be a key component of melanoma development from UV exposure and resistance to platinum chemotherapies." (PMID 29373959, 2018). "We have found that the three GGR components XPC, DDB1 and DDB2 do not respond to UV treatment in melanoma cell lines, resulting in reduced repair of UV-induced DNA damage." (PMID 29373959, 2018). "Expression of GGR components, XPC, DDB1 and DDB2 significantly increased in response to cisplatin in melanocytes but this increase was noticeably absent in melanoma." (PMID 27487145, 2016). "In this first study to investigate NER in melanoma after UVB we have confirmed that GGR is reduced in melanoma by showing delayed repair of both 6-4 PPs and CPDs, particularly in the crucial S-phase of the cell cycle, and lack of induction of XPC, DDB1 and DDB2 after UVB." (PMID 27487145, 2016).
skin cancer (19 papers, 2008 to 2025). "Humans carrying germline mutations in the XPC gene exhibit strong susceptibility to skin cancer due to defective removal via GG-NER of genotoxic, solar UV-induced dipyrimidine photoproducts." (PMID 35530314, 2022). "In this review, we focused on the signaling pathways dysregulated in NMSC and CM, signaling pathways modulating NER's function, proteins linked to signaling pathways affecting XPC's activity, and little information present about XPC's loss and skin cancers." (PMID 34630850, 2021). "The recurrent mutation p.V548AfsX25 affecting the XPC gene and leading to XP group C, a rare severe genodermatosis associated with skin tumours, was first described in Algerian and Moroccan patients at homozygous state." (PMID 22908982, 2012). "It is well documented that loss of XPC reduces life expectancy and causes skin cancers." (PMID 40243939, 2025). "Furthermore, we will also discuss about signaling pathways affecting NER's activity, proteins linked to signaling pathways influencing wild-type XPC's function, and a little information about XPC loss and skin cancer." (PMID 34630850, 2021). "Characterization of the interplay between BER factors and XPC may provide new insights about the occurrence of non-skin cancer upon XPC-deficiency." (PMID 33329698, 2020). "Thus, XPC mRNA levels may be considered as a predictive-diagnostic biological marker protecting from skin cancer since its low expression level is linked to an increased susceptibility to cancer in XPC-mutation carriers." (PMID 33329698, 2020). "XPC knockout in mice has been shown to favor the development of spontaneous as well as UV-induced skin cancers." (PMID 34630850, 2021). "In this review, we will focus on the signaling pathways disrupted in skin cancer, pathways modulating NER's function, including XPC, to disclose signaling pathways associated with XPC loss and skin cancer occurrence." (PMID 34630850, 2021). "Accordingly, all five specific skin cancer genes from the NER class - DDB2, ERCC3, ERCC5, XPA, and XPC - are associated with UV-sensitive skin." (PMID 26856619, 2016). "This review is focused on recent advances in our knowledge of how XPC protein carries out its DNA quality surveillance preventing sunlight-induced skin cancer." (PMID 26521083, 2016). "Identifying novel regulators of XPC deubiquitination could provide more drug-susceptible targets than XPC to modulate XPC activity in the NER process and prevent skin cancer." (PMID 29228550, 2017). "Therefore, the Xeroderma pigmentosum patients deficient in DDB2, XPC, and XPA genes are highly cancer prone and display over 2,000-fold increased incidence rates of skin cancer due to defects in NER pathway." (PMID 27442013, 2016). "XPC defects have been found in many types of cancer, including lung and skin cancer." (PMID 25535740, 2014). "Xeroderma Pigmentosum patients harbouring defects in XPC and DDB2 genes are more prone to develop ocular surface (including the cornea) and skin cancers, demonstrating the importance of DNA repair in cancer prevention of corneal cancer." (PMID 27611318, 2016). "We further determined whether the mechanism of USP11 activity was via regulating deubiquitination of XPC, as well as USP11’s role in skin cancer." (PMID 29228550, 2017). "These insights into the mechanism of USP11 action on XPC deubiquitination and NER suggest that USP11 could be a promising target for treatment of skin cancer." (PMID 29228550, 2017). "It is also noteworthy in this regard that mouse models lacking XPC and/or DDB2 are prone to tumors in internal organs in addition to being sensitive to UV-induced skin tumors." (PMID 33937266, 2021).
colorectal cancer (15 papers, 2014 to 2025). A primary or metastatic malignant neoplasm that affects the colon or rectum. "The XPC rs2228001 polymorphism has been more extensively investigated in relation to colorectal cancer risk, whereas data on its role in predicting response or toxicity to platinum-based regimens remain limited and contradictory." (PMID 41300713, 2025). "Numerous studies have associated SNPs in the XPC gene with various cancer types, including breast and colorectal cancers." (PMID 40833230, 2025). "In conclusion, XPC plays a key role in the susceptibility of colorectal cancer to chemotherapy and ionizing radiation and is associated with a good patients' prognosis." (PMID 30109214, 2018). "We found that a significantly decreased risk of colorectal cancer was associated with XPC polymorphism rs2228000_CT genotype (OR 0.59; p < 0.0001) and the rs2228000_TT genotype (OR 0.29; p < 0.0001) compared to the reference genotype (CC)." (PMID 25391773, 2015). "Logistic regression revealed that the XPC rs2228000_CT or _TT genotype was significantly associated with a decreased colorectal cancer risk." (PMID 25391773, 2015). "A significantly decreased colorectal cancer risk was identified for the XPC rs2228000 (Ala499Val) CT genotype (OR 0.59; p < 0.0001) and for TT genotype (OR 0.29; p < 0.0001) compared to the reference genotype (CC)." (PMID 25391773, 2015). "Importantly, the study investigated the impact of green tea consumption on the odds of having colorectal cancer in carriers of specific XPC polymorphisms." (PMID 40002218, 2025). "The XPC gene plays a crucial role in repairing bulky, helix-distorting DNA lesions, and several polymorphisms in this gene may influence susceptibility to colorectal cancer." (PMID 40002218, 2025). "Similarly in colorectal cancer, increased XPC expression was associated with longer 5 year survival in treated patients compared to patients with low XPC expression." (PMID 35530314, 2022). "XPC may also play a role as a risk factor for other cancers including advanced colorectal cancer." (PMID 35530314, 2022). "An interesting population-based case–control study, including 421 colorectal cancer patients and 845 controls, was conducted in China to assess the association between XPC polymorphisms (Lys939Gln, Ala499Val, and PAT) and colorectal cancer risk." (PMID 40002218, 2025). "In a study corresponding to colorectal cancer in the Chinese population, some NER genetic variants (XPA rs10817938 and XPC rs2607775) were illustrated to alter disease risk." (PMID 38089451, 2022). "XPC siRNA significantly downregulated XPC protein expression in SW1463 and HCT116 colorectal cancer cell line, whereas XPC protein expression was significantly upregulated in the cells transfected with pcDNA3-XPC." (PMID 30109214, 2018). "In order to study the relationship between XPC expression and the progression of HRC, XPC expression was measured in 167 patients with colorectal cancer." (PMID 30109214, 2018). "Our study confirmed that the expression of XPC was closely related with the degree of differentiation of colorectal cancer." (PMID 30109214, 2018). "Our study found that XPC expression in colorectal cancer tissue was significantly higher than that in the normal tissue and XPC overexpression increased the susceptibility of cells to cisplatin and IR in an in vitro experiment." (PMID 30109214, 2018). "The relationship between XPC expression and the development of colorectal cancer was analyzed in the second section of the clinical trial." (PMID 30109214, 2018). "Western blot results revealed that XPC protein appeared at the predicted site of 120 kDa and its expression in the colorectal cancer tissue was significantly higher than its expression in the normal tissue (P < 0.05)." (PMID 30109214, 2018). "Haplotype analysis within XPC, XPD and XPG revealed haplotypes associated with an altered colorectal cancer risk." (PMID 25391773, 2015).
colorectal cancer (continued). "In conclusion, this study suggests that XPC rs2228000 (Ala499Val) and the XPD rs1799793 (Asp312Asn-) polymorphisms are significantly associated with an alteration in colorectal cancer risk." (PMID 25391773, 2015). "Our study found that high XPC expression could improve the prognosis of patients with colorectal cancer by enhancing apoptosis induced by chemotherapeutic drugs." (PMID 30109214, 2018). "FACS results revealed that XPC overexpression promoted SW1463 and HCT116 apoptosis after cisplatin treatment or IR, whereas XPC silencing suppressed apoptosis, demonstrating a role of XPC in the radiotherapeutic and chemotherapeutic resistance of colorectal cancer." (PMID 30109214, 2018). "The high XPC expression in colorectal cancer might be involved in these mechanisms and leading to a better prognosis." (PMID 30109214, 2018). "Cox regression analysis showed that high XPC expression might be a potential predictive factor for colorectal cancer." (PMID 30109214, 2018). "In addition, the expression of XPC in the highly differentiated colorectal cancer tissues was markedly higher than that in the poorly differentiated cancer tissues." (PMID 30109214, 2018). "Among them, only the XPC gene expression was significantly increased in colorectal cancer tissue." (PMID 30109214, 2018). "A meta-analysis that included 6 studies examined XPC rs2228001 as a risk factor for colorectal cancer (2,751 cases and 3,607 controls) but failed to include studies examining the role of XPC rs2228000." (PMID 25391773, 2015). "In this case–control study that included 758 patients with colorectal cancer and 1,841 healthy adults, we found that the XPC rs2228000 (Ala499Val) and the XPD rs1799793 (Asp312Asn-) polymorphisms were significantly associated with an altered colorectal cancer risk." (PMID 25391773, 2015). "Our results confirmed that polymorphisms in XPC and XPD may be associated with the risk of colorectal cancer." (PMID 25391773, 2015). "However, XPC is involved in several processes including cell cycle regulation, cell apoptosis and DNA damage repair, which undoubtedly provides new evidences in the occurrence, development and multi-drug resistance of colorectal cancer." (PMID 30109214, 2018). "In the other study, which evaluated 421 colorectal cancer patients and 845 healthy individuals the results suggested that the CC genotype in the Lys939Gln and PAT +/+ genotype in an intronic biallelic poly(AT) insertion/deletion polymorphism in XPC increased CRC risk." (PMID 25391773, 2015). "In the present study, the expression of NER genes (XPC, XPA, XPG, XPF, ERCC1, and XPD) was measured in human colorectal cancer and the corresponding normal tissues." (PMID 30109214, 2018). "Therefore, our study preliminarily proved that XPC might play an important predictiverole in the progression of colorectal cancer, although the mechanism is not yet clear." (PMID 30109214, 2018).
Xeroderma pigmentosum complementation group C (13 papers, 2012 to 2025). "In this study, they achieved read-through in skin-disorder (xeroderma pigmentosum complementation group C, XPC) patient-derived fibroblasts expressing the XPC gene with a nonsense mutation (1840C > T, Arg579X)." (PMID 32575694, 2020). "The genes XPC (xeroderma pigmentosum, complementation group C) and ERCC3 (XPB) are particularly relevant to NER in MM." (PMID 41155462, 2025). "The treatment of 3D skin models with B[a]P resulted in an increase in the expression of xeroderma pigmentosum complementation group C (XPC) and XPG proteins, both of which are typical representatives of this repair pathway." (PMID 34579573, 2021). "Here we show that ubiquitin-specific peptidase 11 (USP11) positively regulates NER by deubiquitinating xeroderma pigmentosum complementation group C (XPC) and promoting its retention at the DNA damage sites." (PMID 29228550, 2017). "The xeroderma pigmentosum complementation group C (XPC) is one of the eight core genes (i.e., ERCC1, XPA, XPB, XPC, XPD, XPE, XPF, and XPG) in the nuclear excision repair (NER) pathway of the DNA repairing system." (PMID 24886180, 2014). "More close analysis at the LOOCV (leave one out cross validation analysis) result points to the rs2228001 in XPC (xeroderma pigmentosum complementation group C) gene contributing mostly to this predictive potential." (PMID 22666610, 2012).